CLN6 (CLN6 transmembrane ER protein)
Diseases named in the same sentence as CLN6 in open-access papers (continued):
Sharing a sentence is not in itself a finding about the gene and the disease.
retinal dystrophies (1 paper, 2021). "A critical role of inflammatory immune responses in the progression of retinal dystrophies in NCL has also been demonstrated in mouse models of CLN1, CLN3 and CLN6 disease." (PMID 33800998, 2021).
uveal melanoma (1 paper, 2025). A melanoma derived from melanocytes of the uveal tract. "A study focusing on glycolysis-related genes and their link to uveal melanoma prognosis identified CLN6 as a gene associated with the prognosis of uveal melanoma." (PMID 40821828, 2025).
neurodegenerative disease (7 papers, 2013 to 2023). A disorder of the central nervous system characterized by gradual and progressive loss of neural tissue and neurologic function. "Contributes to lysosomal function as well as the viability of neurones; mutations in CLN6 have shown to cause neurodegenerative disease; CLN6 is also associated with mTOR and TELO2 regulators of signaling pathways that are known to be disrupted by ZIKV." (PMID 35371036, 2022). "A mutation of CLN6 would result in neuronal ceroid lipofuscinoses (NCLs), the most common neurodegenerative disease, which primarily occur in children." (PMID 34383793, 2021). "Further to our investigation of metal concentrations, we assessed the expression of synaptic proteins in the CLN6 affected brains, as synaptic loss is a characteristic feature of several neurodegenerative diseases." (PMID 23516525, 2013). "This study demonstrates the central role of the metal transporter, Zip7, in the aberrant biometal metabolism of CLN6 variants of NCL and further highlights the key contribution of deregulated biometal trafficking to the pathology of neurodegenerative diseases." (PMID 24581221, 2014).
mitochondrial disease (2 papers, 2013 to 2022). "CLN6 and other non mitochondrial nuclear genes were included in our panel as the associated clinical presentation can be easily confused with mitochondrial disease." (PMID 24215330, 2013).
neurological diseases (2 papers, 2022 to 2024). "Because these are shared by other neurological diseases, identification of CLN6 genetic variants is imperative for early diagnosis." (PMID 35505348, 2022). "This indicates that the CLN6 variant is not a common cause of neurological disease in mixed-breed dogs." (PMID 38927597, 2024). "In a small sample of 13 mixed-breed dogs with neurological disorders of unknown etiology, none had the CLN6 splice site variant." (PMID 38927597, 2024).
tumor (1 paper, 2025). "The four-gene signature (CLN6, GMPR, AP1S2, ITGA6) and their validated roles in proliferation/migration (e.g., CLN6 knockdown suppressing tumor growth) provide novel therapeutic targets." (PMID 40821828, 2025).
CLN6 also shares sentences with these, for which no sentence is quoted: retinopathies (2 papers); Ataxia (1); Atrophy (1); cutaneous melanoma (1); dementia (1); Developmental regression (1); Dyskinesia (1); Gaucher disease (1); GM1 gangliosidosis (1); Kanzaki disease (1); Kaya-Barakat-Masson syndrome (1); Kufor-Rakeb syndrome (1); Morquio A disease (1); neurodevelopmental disorder (1); Onset (1); Parkinsonism (1); Retinal atrophy (1); Schindler disease (1); Seizure (1); sphingolipidoses (1); Unverricht-Lundborg disease (1); vision impairment (1); Wolman disease (1).